SH3GL1 (SH3 domain containing GRB2 like 1, endophilin A2)
Description:
Implicated in endocytosis. In a first step mediates neck formation during ultrafast endocytosis and function at a second step to aid in the removal of clathrin coats from the regenerated vesicles (By similarity). May recruit other proteins to membranes with high curvature (By similarity).
Synonyms: EEN; CNSA1; SH3D2B; SH3P8; MGC111371
Tractability: Antibody: UniProt places it where antibodies can reach, with medium confidence. PROTAC: ubiquitination databases record sites on it; its protein half-life has been measured.
Gene: Protein-coding gene on chromosome 19 (4,360,367 to 4,400,547, reverse strand). Ensembl gene ENSG00000141985.
Subcellular location: Cytoplasm; Early endosome membrane; Cell projection, podosome
Subcellular location (Human Protein Atlas): Cytosol
Pathways (Reactome):
Signal Transduction: EGFR downregulation; Negative regulation of MET activity
Vesicle-mediated transport: Cargo recognition for clathrin-mediated endocytosis; Clathrin-mediated endocytosis
Disease: InlB-mediated entry of Listeria monocytogenes into host cell
Gene Ontology:
Molecular function: cadherin binding; identical protein binding; protein binding; protein-macromolecule adaptor activity
Biological process: central nervous system development; endocytosis; membrane organization; signal transduction; synaptic vesicle endocytosis; synaptic vesicle recycling; vesicle uncoating
Cellular component: cytoplasm; cytosol; glutamatergic synapse; membrane; presynapse; early endosome membrane; podosome
Genetic constraint (gnomAD): Loss-of-function variants: 21 observed, 48.91 expected, observed/expected ratio (o/e) 0.43, 90% interval 0.3 to 0.62. The synonymous counts are far from expectation, so gnomAD's model fits this gene poorly and the ratio says little. Missense variants: 454 observed, 508.89 expected, observed/expected ratio (o/e) 0.89, 90% interval 0.82 to 0.96. Synonymous variants: 282 observed, 221.47 expected, observed/expected ratio (o/e) 1.27, 90% interval 1.15 to 1.4.
Homologues: Orthologues: chimpanzee SH3GL1 (99% identical), pig SH3GL1 (97% identical), macaque SH3GL1 (97% identical), mouse Sh3gl1 (94% identical), dog SH3GL1 (92% identical), guinea pig SH3GL1 (92% identical), rat Sh3gl1 (88% identical), tropical clawed frog sh3gl1 (84% identical), zebrafish sh3gl1b (74% identical), zebrafish sh3gl1a (65% identical), Drosophila melanogaster Dlish (16% identical), Caenorhabditis elegans B0303.7 (12% identical). Paralogues in human: SH3GL2 (70% identical), SH3GL3 (66% identical), SH3GLB1 (29% identical), SH3GLB2 (27% identical), SORBS1 (23% identical), SORBS2 (20% identical), SH3D19 (19% identical), SH3RF3 (18% identical), SH3RF1 (17% identical), SORBS3 (16% identical), NCF4 (15% identical), SH3RF2 (13% identical).
Diseases named in the same sentence as SH3GL1 in open-access papers:
SH3GL1 is named in the same sentence as 34 diseases in open-access papers, as found by Europe PMC text mining. Sharing a sentence is not in itself a finding about the gene and the disease. The quoted sentences say what the papers report.
breast carcinoma (5 papers, 2017 to 2025). "In addition, in HER2-positive breast cancer, Endophilin A2 (encoded by SH3GL1) has been shown to increase HER2 internalization and enhance the sensitivity of breast cancer cells to trastuzumab-based therapy." (PMID 37298631, 2023). "Endophilin A2, encoded by the SH3GL1 gene, has been demonstrated to promote HER2 internalization and enhance the sensitivity of breast cancer cells to trastuzumab-based therapies." (PMID 40843356, 2025).
acute myeloid leukemia (2 papers, 2013 to 2015). Acute myeloid leukemia (AML) is a group of neoplasms arising from precursor cells committed to the myeloid cell-line differentiation. "The epigenetic alteration results in its reduced expression level, and in turn increases the expression of SH3GL1 by reducing ATF3-mediated inhibition of SH3GL1, which is a fusion partner in acute myeloid leukemia and plays a role in leukemogenesis." (PMID 26169043, 2015).
autoimmune disease (2 papers, 2021 to 2023). A disorder resulting from loss of function or tissue destruction of an organ or multiple organs, arising from humoral or cellular immune responses of the individual to their own tissue constituents. "Since EA2 deficiency had such a great impact on T cell dependent autoimmune disorders we investigated if the expression of SH3gl1 increased in T cells after arthritis induction." (PMID 33504785, 2021). "We show that deficiency of SH3gl1 leads to a complete protection against autoimmune diseases in both mutated DA rats and in SH3gl1 knockout mice and that this results from loss of T cell effector functions." (PMID 33504785, 2021). "Collectively our data identify SH3GL1 as a key regulator of T cell activation, and as a potential target for treatment of autoimmune diseases." (PMID 33504785, 2021). "Using a rat animal model of RA, we discovered SH3GL1 as a major regulator of T cell effector function and autoimmune diseases." (PMID 33504785, 2021).
diffuse large B-cell lymphoma (2 papers, 2021 to 2025). "Correction between SH3GL1 protein expression and characteristics of diffuse large B‐cell lymphoma (DLBCL) patients from Jiangsu Provincial Hospital DLBCL (JSPHDLBCL) database." (PMID 40038872, 2025).
glioma (2 papers, 2012 to 2018). A benign or malignant brain and spinal cord tumor that arises from glial cells (astrocytes, oligodendrocytes, ependymal cells). "The immunological reaction to SH3GL1 would contribute to the establishment of a novel diagnostic and therapeutic target for gliomas." (PMID 23050879, 2012). "Among them, the serum level of autoantibody to src-homology 3-domain GRB2-like 1 (SH3GL1) was significantly higher in patients with low-grade glioma than healthy volunteers or high-grade gliomas." (PMID 23050879, 2012). "The levels of serum autoantibodies to SH3GL1 were significantly higher in patients with low-grade gliomas than in healthy donors by ELISA." (PMID 23050879, 2012). "In high-grade gliomas, the tissue expression of SH3GL1 was further increased, but the immune response was suppressed." (PMID 23050879, 2012). "The rat glioma model using C6 and 9 L glioma cells also showed the increases of the anti-SH3GL1 autoantibody level in the early stage and decreases in the late stage." (PMID 23050879, 2012). "It should be noted that we found autologous antibodies against SH3GL1 to be a low-grade glioma-specific marker with similar experimental systems to others." (PMID 23050879, 2012). "To confirm the changes in the serum anti-SH3GL1 autoantibody level, we used rat glioma models with C6 and 9 L cells which expressed its messenger RNA (data not shown)." (PMID 23050879, 2012). "The levels of serum antibodies to SH3GL1 were significantly higher in patients with low-grade glioma than those with high-grade glioma (P = 0.0243) and healthy volunteers (P = 0.0045)." (PMID 23050879, 2012). "The rat glioma models confirmed the increase of anti-SH3GL1 autoantibody level in the early stage and the suppression in the late stage." (PMID 23050879, 2012). "Overall survival of the patients with low-grade gliomas according to the serum level of anti-SH3GL1 autoantibody was analyzed by Kaplan-Meier analysis." (PMID 23050879, 2012). "In the present study, the authors applied SEREX to glioma to find SH3-domain GRB2-like 1 (SH3GL1) as a novel glioma-related antigen." (PMID 23050879, 2012). "The tissue expression of SH3GL1 protein increased in proportion to glioma progression." (PMID 23050879, 2012). "The major cause of the lower level of anti-SH3GL1 autoantibody in high-grade glioma patients would be the non-specific immunosuppression caused by increased immunosuppressive cytokines." (PMID 23050879, 2012). "SH3GL1 may be involved in the oncogenic process of gliomas and effectively elicit an autologous antibody response in low-grade gliomas." (PMID 23050879, 2012). "The level of anti-SH3GL1 autoantibody could be a novel low-grade glioma-specific serum marker." (PMID 23050879, 2012). "In glioma tissues, strong positive staining of SH3GL1 was obtained in the cytoplasms but not in the nucleus, and the levels of staining in white matter increased according to the advance of its malignancy." (PMID 23050879, 2012). "In glioma tissues, strong positive staining of SH3GL1 was observed in the cytoplasms but not in the nucleus." (PMID 23050879, 2012). "However, the levels of serum autoantibodies to SH3GL1 in the patients with high-grade glioma were not increased in our study, while the levels in the patients with low-grade glioma were increased." (PMID 23050879, 2012).
leukaemia (2 papers, 2018 to 2025). "Interestingly, the leukemia-associated AML1-ETO fusion gene upregulates SH3GL1 expression, further contributing to leukemogenesis by promoting proliferation and myeloid transformation." (PMID 40986063, 2025).
Arthritis (1 paper, 2021). Inflammation of a joint. "In this model of septic arthritis, we did not observe any difference in bacterial clearance or development of arthritis in SH3gl1 deficient mice compared to wild-type littermates." (PMID 33504785, 2021). "Here we show, using a forward genetic approach, that a mutation in the SH3gl1 gene encoding the endocytic protein Endophilin A2 is associated with the development of arthritis in rodents." (PMID 33504785, 2021). "To confirm that the arthritis resistance was intrinsic to T cells, we transferred thymocytes from SH3gl1 deficient or wild-type littermate mice into TCRβ knockout mice before the induction of glucose-6-phosphate isomerase (GPI) induced arthritis." (PMID 33504785, 2021). "Similar to the DAMut rats, the SH3gl1 deficient mice were also protected from arthritis, in contrast to their SH3gl1 sufficient wild-type littermates." (PMID 33504785, 2021). "To confirm that the arthritis resistance observed in the DAMut rats was due to a deficiency in EA2 expression we introgressed a deletion of the SH3gl1 gene into arthritis-susceptible B6N.Q mice through backcrossing and evaluated them with collagen-induced arthritis (CIA)." (PMID 33504785, 2021). "Because of the importance of TCR internalization and formation of the immunological synapse for efficient TCR signaling, a lack of SH3GL1 leads to reduced T cell signaling and would subsequently result in reduced numbers of autoreactive T cells, in turn limiting the arthritis development." (PMID 33504785, 2021).
Autoimmunity (1 paper, 2021). The occurrence of an immune reaction against the organism's own cells or tissues. "We demonstrate that deficient expression of SH3gl1, caused by either a spontaneous mutation in the DA rat, or in genetically modified mice, leads to protection against autoimmunity." (PMID 33504785, 2021).
breast tumors (1 paper, 2017). "The expression of ABHD11, ADORA2B, E2F1, EZH2, PAICS, SFN and SH3GL1 was significantly higher in grade III than in grade I breast tumors." (PMID 28411283, 2017).
low grade glioma (1 paper, 2012). A grade I or grade II glioma arising from the central nervous system. "The same results of both ELISA based on the independent serum sets support the possibility that SH3GL1 is aberrantly expressed and efficiently elicits a systemic immune response in low-grade glioma patients." (PMID 23050879, 2012).
lymphoma (1 paper, 2025). A malignant (clonal) proliferation of B- lymphocytes or T- lymphocytes which involves the lymph nodes, bone marrow and/or extranodal sites. "In this current study, our findings showed that SH3GL1 was upregulated in lymphoma cell lines, including DLBCL cell lines, CLL cell lines, MCL cell lines, BL cell lines and ALCL cell lines." (PMID 40038872, 2025).
medulloblastoma (1 paper, 2025). A malignant, invasive embryonal neoplasm arising from the cerebellum. "Interestingly, SH3GL1 overexpression has been linked to downregulation of tumor-suppressive microRNAs: in medulloblastoma cells, reduced miR-218 increases SH3GL1 expression, which stimulates ERK activation and cell proliferation." (PMID 40986063, 2025).
melanoma (1 paper, 2021). A malignant, usually aggressive tumor composed of atypical, neoplastic melanocytes. "To further challenge the immune system in EA2 deficient mice, we injected SH3gl1 deficient and wild-type littermate mice with B16F10 melanoma cells and followed tumor growth." (PMID 33504785, 2021).
mucinous tumors (1 paper, 2012). "These include: FH, GMPS, PIK3CA, EIF4A2, ZNF384, and SS18L1 (amplifications in serous tumors); TET2, FGFR10P, NF1, ERBB2, and SH3GL1 (deletions in serous tumors) and ERBB2 (amplifications in mucinous tumors)." (PMID 23078675, 2012).
rheumatoid arthritis (1 paper, 2021). A chronic, systemic autoimmune disorder characterized by inflammation in the synovial membranes and articular surfaces. "We further show that SH3GL1 regulates human T cell signaling and T cell receptor internalization, and its expression is upregulated in rheumatoid arthritis patients." (PMID 33504785, 2021).
serous cystadenocarcinoma (1 paper, 2013). A malignant serous cystic neoplasm usually involving the ovary or the pancreas. "In particular, the NBP2/nbp2 heterozygote is multiply drug-hypertolerant, of note since its ortholog SH3GL1 frequently has reduced copy-number in serous cystadenocarcinoma." (PMID 23531409, 2013).
tumor (12 papers, 2012 to 2025). "Knockdown of SH3GL1, which encodes endophilin A2 in tumor cells, reduced internalization and suppressed T-DM1-mediated cytotoxicity." (PMID 39001482, 2024). "The protein levels of SH3GL1 (SH3 Domain Containing GRB2 Like 1, Endophilin A2) were linked to tumor progression, metastasis, and worse patient outcomes in many cancer types." (PMID 39268460, 2024). "A significant decrease of tumour volume was observed in the absence of SH3GL1 compared to SH3GL1 wild‐type group, along with decreased SH3GL1 protein level in SH3GL1 knock out tumours." (PMID 40038872, 2025). "Taken together, these results suggested that SH3GL1 is integral to both in vitro cell proliferation and in vivo tumour formation." (PMID 40038872, 2025). "In the C6 glioma model, the serum levels of autoantibody to SH3GL1 significantly increased in the rats at 2-week after tumor inoculation compared with those at 3-day after the inoculation (p = 0.0028)." (PMID 23050879, 2012). "Meanwhile, lower level of FTH1 was also observed in SH3GL1 knockout xenograft mouse tumour tissues." (PMID 40038872, 2025). "Moreover, endophilin A2, a protein involved in clathrin-independent endocytosis and encoded by SH3GL1, increases HER2 internalization in patients with HER2-positive BC and is associated with a higher response of tumor cells to T-DM1 and trastuzumab." (PMID 39050884, 2024). "Like SH3GL1, SH3GL3 expression is lower in glioblastoma compared to healthy brain tissues, with further reduction in higher-grade gliomas, suggesting tumor- suppressive roles." (PMID 40986063, 2025).
cancer (7 papers, 2012 to 2025). A tumor composed of atypical neoplastic, often pleomorphic cells that invade other tissues. "Similarly, cancer autoantibody biomarkers, such as SH3GL1-Abs and striatin 4-Abs, were associated with high antigen expression in the cancer tissues." (PMID 38732153, 2024). "We used the R package ‘Limma’ within RStudio, and results showed that SH3GL1 is an essential gene for DLBCL cell survival compared to other cancer cell lines." (PMID 40038872, 2025). "Although there are few reports describing overexpression of this protein in human cancers, SH3GL1 protein is related to the activation of MLL proto-oncogene by chromosomal translocation." (PMID 23050879, 2012). "Therefore, this study highlights SH3GL1 as a novel regulator of ferroptosis in DLBCL, suggesting that targeting SH3GL1 may be a promising strategy to prevent DLCBL progression and overcome the resistance to traditional cancer treatments." (PMID 40038872, 2025).
SH3GL1 also shares sentences with these, for which no sentence is quoted: Burkitt lymphoma (2 papers); infection (2); prostate carcinoma (2); acute leukemia (1); anaplastic large cell lymphoma (1); bacterial infections (1); B‐cell lymphoma (1); cardiovascular diseases (1); colorectal cancer (1); glioblastoma (1); high-grade glioma (1); mantle cell lymphoma (1); multiple myeloma (1); myocardial infarction (1); septic arthritis (1); virus infection (1).